EGFR (epidermal growth factor receptor)
Diseases named in the same sentence as EGFR in open-access papers (continued):
Sharing a sentence is not in itself a finding about the gene and the disease.
cancer (continued). "Cellular migration and invasion is inhibited by blocking EGFR and consequently its pathways, by a monoclonal antibody (mAb) or a tyrosine kinase inhibitor (TKI), suggesting a crucial role for EGFR inhibitors in the control of cancer metastasis." (PMID 26635612, 2015). "EGFR is overexpressed in numerous cancer types, including non-small cell lung, breast, prostate and colorectal cancer." (PMID 25435943, 2015). "The expression of other cancer tissue markers (CK7, CK5/6, p63) did not correlate with the occurrence of EGFR mutations." (PMID 25086987, 2015). "Our data demonstrate that CXCR2 contributes to IL-1β-mediated EGFR transactivation in OSCC and may provide an explanation for the oncogenic effect of CXCR2 in this cancer." (PMID 26462152, 2015). "Previous research showed that EGFR co-immunoprecipitates with ERα and GPER, suggesting that an intricate crosstalk may occur among these main transduction mediators in cancer cells." (PMID 25616260, 2015). "In many cancers, these alternative RTKs including MET, IGF1R, FGFR and EphA2 become activated or amplified in order to maintain the signals for cell survival and/or proliferation in common downstream pathways, thus nullifying the inhibition of EGFR kinase." (PMID 25599599, 2015). "In addition, considering the remediability of EGFR, indicating that EGFR could be targeted by monoclonal antibodies or small therapeutic molecules, including cetuximab and gefitinib and therefore treat cancer, it may be a potential option for the treatment of AdCC." (PMID 25997612, 2015). "Moreover we showed that, besides EGFR, matrix metalloproteases (MMP) were crucial for macrophage-mediated cancer cell invasion, since the presence of a broad MMP inhibitor (Galardin) was able to abolish this effect." (PMID 26043921, 2015). "Survival is often promoted in tyrosine kinase-driven cancers such as CML and EGFR NSLCL, through repression of Bim transcription and through targeting the Bim protein for proteasomal degradation following Mitogen-activated protein kinase 1 (MAPK1/ERK2)-dependent phosphorylation." (PMID 26405162, 2015). "Using several cell lines as a model of classical GBM, a type characterized by high endogenous levels of EGFR, we found that CrkY251 phosphorylation, induced downstream of EGFR activation, is a frequent event in GBM cells and correlates with aggressive cancer phenotypes." (PMID 26473374, 2015). "Neither treatment with MG132 nor with Chloroquine showed an effect on the ANO1-knockdown induced reduction of EGFR-protein levels, indicating that ANO1 does not affect the general turnover of EGFR in cancer cells." (PMID 25823819, 2015). "Epidermal growth factor receptor (EGFR) pro-proliferative signaling activity is commonly elevated in cancer, and the EGFR inhibitor erlotinib is commonly used as a standard of care agent for cancer." (PMID 26528438, 2015). "The finding that all EGFR mutant SCLC transformed samples have low/absent EGFR expression compared with pre-resistant controls provides insight into the explanations for the lack of sensitivity of these cancers to TKI." (PMID 25758528, 2015). "Following this, EGFR-TKIs have been reported to act as radiosensitizers in NSCLC and other cancers." (PMID 25714021, 2015). "In addition to HER3/EGFR dimerization, HER3/HER2 dimerization is also observed in many tumors, it suggesting that HER3 also is required for cancer cell survival and proliferation." (PMID 26035354, 2015). "One case (#11) showed amplification of HER2 and EGFR in different metastases, and had no HER2/EGFR co-amplified primary cancer spots." (PMID 25649416, 2015). "They appear to downregulate epidermal growth factor receptor (EGFR), protein kinase C (PKC), Ras, NF-κB, and insulin-like growth factor (IGF), which are important cell-signaling mediators often found to be elevated in cancer." (PMID 26339635, 2015).
cancer (continued). "Previously, we have found that, independent of its kinase activity, EGFR interacts with FASN at the plasma membrane in cancer cells." (PMID 26378037, 2015). "Some previous studies have revealed that EGFR and integrin-β1 regulate MMP-7 expression; however, to the best of our knowledge, it has not been previously reported that integrin-α2, MRLC and YAP regulate MMP-7 expression in cancers." (PMID 26344692, 2015). "In accordance with these observations, in BG-1 and 2008 cancer cells the silencing of GPER or ERα expression and the inhibition of the EGFR/ERK signaling prevented the action of atrazine, confirming that a cooperation between these receptors is involved in the biological responses to atrazine." (PMID 25616260, 2015). "So far, the common cancer-driver genes identified in NSCLC include the mutant activations of Kirsten rat sarcoma (KRAS), epidermal growth factor receptor (EGFR), proto-oncogene B-Raf (BRAF), and phosphoinositide-3-kinase, catalytic, α polypeptide gene (PIK3CA)." (PMID 26227959, 2015). "This implicates CIP4 in both EGFR-driven TNBCs (this paper), and HER2-driven cancer cell invasion." (PMID 25823823, 2015). "Finally, a crosstalk between ανβ3 integrin and epidermal growth factor receptor (EGFR) has been shown, through which cancer cell invasion and metastasis are stimulated." (PMID 25629807, 2015). "Since amplification of EGFR is an important driver of tumorigenesis in GBM (as evident from cancer genome sequencing analysis), we explored the Crk Tyr251/Abl axis in several GBM cells lines, that de-regulate EGFR, using phosphospecific antibodies to AblY245 and CrkY251." (PMID 26473374, 2015). "Having shown that ANO1 and EGFR form a functional complex and that EGFR-signaling regulates ANO1-protein levels in cancer cells, we wondered whether ANO1 would affect EGFR protein levels in these cells." (PMID 25823819, 2015). "Although linage specific analysis in RNAi data excluded genes that are important drivers for multiple cancers as well as ESCC, such as ERBB2 and EGFR, through knockdown assays in ESCC cell lines and additional survival analysis, we confirmed GRB7 as a new driver gene in ESCC." (PMID 26465158, 2015). "However, this is the first study to demonstrate that digoxin can inhibit not only Src but also the phosphorylation and expression of EGFR and STAT3 to further retard cancer cell proliferation, migration and invasion." (PMID 25955608, 2015). "Because of the involvement of dysregulated EGFR signaling and an inflammatory microenvironment in oral tumorigenesis, converging these 2 oncogenic events has a profound effect on the etiology of OSCC and the clinical management of this cancer." (PMID 26462152, 2015). "In cultured cancer cells Src co-localized with E-cadherin in cell-cell junctions and its phosphorylation on Y419 was both constitutive and independent of EGFR activation." (PMID 25779657, 2015). "NEU3 enhances cancer cell survival, cell migration and attachment, whereby it stimulates Ras activation with a consequent influence on ERK1/2 and Akt and actually enhances the EGF-stimulated tyrosine-phosphorylation of EGFR." (PMID 25803810, 2015). "A647-labeled PVX nanoparticles, bioconjugated with a 12 amino acid peptide with affinity to the epidermal growth factor receptor (EGFR), are effective in detection and imaging of carcinoma cell lines that upregulate EGFR, and prefer partitioning to cancer cells rather than to macrophages." (PMID 26635836, 2015).
cancer (continued). "EGFR and pEGFR were nearly absent in glandular epithelial cells of colorectal mucosa adjoining cancer tissue.ErbB2 immunoreactivity was observed in cancer cells in 41 cases (26%; 16% with score 2+ and 10% with score 3+)." (PMID 25416285, 2014). "EGFR inhibitory antibodies such as Cetuximab can lead to responses and survival benefit in KRAS wildtype cancers, but the role of EGFR amplification is not clear." (PMID 24968263, 2014). "Serial biopsies revealed that these genetic mechanisms of resistance were lost in the absence of the continued selective pressure of EGFR inhibitor treatment, and such cancers were sensitive to a second round of treatment with EGFR inhibitors." (PMID 24722523, 2014). "Furthermore, a recent study demonstrated cancer cells under hypoxia up-regulate ADAM12-L expression, leading to increased HB-EGF shedding, EGFR activation, formation of invadopodia, and cancer invasion." (PMID 24651654, 2014). "They confirmed that the specific inhibition of the EGFR mutated allele, represents a safe and effective progress for cancer therapy, also because ASP-RNAi treatment can suppress cancer cell proliferation and growth, regardless of sensitivity to EGFR-TKIs." (PMID 25593996, 2014). "Correlation of drug activities with cancer gene mutations revealed novel drug sensitivity markers, suggesting that cancers dependent on mutant CTNNB1 will respond to trametinib and other MEK inhibitors, and cancers dependent on SMAD4 to small molecule EGFR inhibitor drugs." (PMID 24651269, 2014). "This is theoretically plausible considering that T790M only reduces the biding affinity of EGFR-TKIs, but does not activate the redundant mechanism for cancer-cell survival except in rare cases having other concomitant, resistant mechanisms." (PMID 25486409, 2014). "PTPD1, EGFR and c-SRC could then regulate actin and membrane dynamics needed to propagate EGF signals and consequently promote cancer progression." (PMID 25062045, 2014). "Because many receptor proteins (e.g., EGFR, PDGFRA, PDGFRB, ERBB2, and ERBB4) are typically located in the upstream of cancer-related signaling pathways such as proliferation, cell death, and cell cycle progression, mutations in these genes are likely critical to cancer development." (PMID 24516372, 2014). "Furthermore, CNAs, as often reported in clinical samples, were detected in the regions of some cancer-related genes; for example, copy number gains of FGFR1, EGFR and PDGFRA in H1703, amplification of MYC and a homozygous loss of CDKN2A in LC2/ad." (PMID 25378332, 2014). "Moreover, our previous study reported that HGF was overexpressed in the EGFR mutant cancer cells that acquired resistance to EGFR-TKIs, indicating endogenous HGF production by cancer cells." (PMID 24952482, 2014). "The EGFR signaling pathway, including its multiple downstream pathways, such as PI3K/AKT, ERK1/2, JAK/STAT3 and mTOR/NF-κB, plays an important role in the regulation of proliferation, survival, migration and chemoresistance in cancer cells." (PMID 24586249, 2014). "For example, miR-145 could suppress cancer cell proliferation by targeting growth factor-related genes such as IRS-1, IGF-IR or epidermal growth factor receptor (EGFR) 85–87." (PMID 25124875, 2014). "As the c-Met and EGFR pathways play an essential role in cancer stem cell maintenance, we asked whether the HGF/c-Met and EGF/EGFR pathways influence ACSVL3 expression in GBM stem cell enriched neurospheres." (PMID 24893952, 2014). "Notably, in a recent project for prioritization of cancer antigens, 4 of the 75 selected antigens were gangliosides (GD2, GD3, fucosyl-GM1, and N-acetyl GM3), and additional targets, like the EGFR and the VEGFR, are known to interact with gangliosides." (PMID 25101077, 2014). "Overall, changes in the expression of EGFR-pathway proteins were lowest in normal liver, higher in normal colon, and highest in cancer tissue." (PMID 25526028, 2014).
cancer (continued). "Metformin may be considered to simultaneously target multiple protein kinases in cancer cells, such as AMPK, S6K1, human epidermal growth factor receptor 1 (HER1), HER2 and Src." (PMID 25289085, 2014). "EGFR activation can be inhibited by small molecule tyrosine kinase inhibitors (TKI), and inhibition of EGFR function has been shown to decrease the growth of several types of human cancer in preclinical researches[15∼18]." (PMID 25000529, 2014). "In this section we will consider two of these proteins, both of which are directly related to cancer: EGFR, which is also identified by iPAC, and NRP1, which is not identified by iPAC." (PMID 24669769, 2014). "Here we showed that L861R activates EGFR in the absence of the activating EGF ligand, suggesting that it is also likely to be cancer-associated." (PMID 24743239, 2014). "Interestingly, previous reports indicated TCDD stimulated EGFR activation in cancer cells, and TCDD-activated AhR can cross talk with EGFR signaling." (PMID 24927102, 2014). "KRAS-mutant cancer is unresponsive to EGFR inhibitors because oncogenic KRAS is not dependent on upstream activation by EGFR." (PMID 25004126, 2014). "Such qualities are often a characteristic of trophic membrane receptor complexes like EGFR, HER2/neu, IGF-1R, and VEGFR that are each over-expressed by several neoplastic cell types including adenocarcinomas and carcinomas that affect the breast, ovary, prostate, lung and intestine." (PMID 25844392, 2014). "Furthermore, the present study verified the expression of the cancer invasion-related genes, MMP-1, MMP-2, EGFR and COX-2, which were upregulated in the CD44+ GC cells, indicating a capacity to manipulate cancer invasion and even metastasis." (PMID 23833643, 2013). "In a previous report, EGFR was significantly more expressed in stage IIIA when compared to earlier stages (I-II), suggesting that expression increases stepwise from precancerous lesions to more advanced stages of cancer." (PMID 26317020, 2013). "Patients with advanced cancers historically known to overexpress EGFR and/or HER2 were preferentially eligible as they could potentially obtain greater clinical benefit from ErbB inhibition." (PMID 23161334, 2013). "However, plasma from donor 7 showed a very distinct phenotype of exosomes carrying higher levels of EGFR, HER2, CD276 and osteopontin; all known cancer antigens." (PMID 24009888, 2013). "Because genetic alterations in RTKs, such as FGFRs, EGFR, HER2, MET, ALK, and RET, drive human cancers, small-molecule inhibitors and human/humanized monoclonal antibodies targeted against RTKs have been developed as cancer therapeutics." (PMID 25364706, 2013). "Moreover, the inhibition of HER3 has been shown to be more relevant than the inhibition of EGFR and HER2 in breast and lung cancer models." (PMID 23700486, 2013). "As drug resistance of cancer cells is one of the important reasons for therapeutic failure or cancer recurrence, we asked whether the Y211F CPPP is also effective in the EGFR TKI-resistant TNBC cells." (PMID 23593472, 2013). "In cases where cancer cells express both proHB-EGF and EGFR, the same cell may act as the donor and the acceptor of the cell survival and proliferation signals." (PMID 23349913, 2013). "Unlike the widely studied erbB2 and EGFR in human cancers, there has been relatively less emphasis on erbB3 as a molecular target for cancer treatment." (PMID 24215614, 2013). "It is expected that the EGFR targeted NIRF probe can not only image HCCs noninvasively but also provides a tool for image-guided therapy, whereas the PET probe can find more broad applications for clinical cancer imaging." (PMID 23710458, 2013). "Thus, mTOR inhibitors achieve growth inhibition by suppressing both survival signals from EGFR and resistance signals from MET in cancer cells." (PMID 23690929, 2013).
cancer (continued). "Abnormal cell cycle regulation due to Cyclin D1 overexpression is a common occurrence in human cancers (including NPC), and both EGFR and STAT3 could target cyclin D1 promoter activity." (PMID 24499623, 2013). "EGFR TKI gefitinib was demonstrated as a potential substrate for BCRP/ABCG2, and combinatory treatment with gefitinib was also found to overcome the BCRP/ABCG2-mediated resistance to some anti-cancer drugs." (PMID 24391798, 2013). "Thus, a coordinated transcription-splicing program controlled by EGFR activation is responsible for the expression of the PKM2 isoform and for the distinctive metabolic features of cancer cells." (PMID 24078813, 2013). "HO1 also augments cancer cell migration and invasion by inducing MMP-9, CD147, and EGFR." (PMID 24180625, 2013). "EGFR inhibitors also increased TRAIL-induced apoptosis in lung and bladder cancer cells suggesting that this may be a generalizable process." (PMID 25520884, 2013). "In agreement with the partial responsibility of p-Akt activation in invasion of some cancer cell lines expressing N-cadherin, we found that erlotinib blocked EGFR and ERK phosphorylation but not Akt phosphorylation in the erlotinib-resistant H1650ER cells." (PMID 23520479, 2013). "Given that there are no known naturally occurring activating mutations in the STAT3 gene, aberrant activation of STAT3 in many types of cancers is primarily due to overexpression or deregulation of upstream signaling molecules such as IL-6/gp130, EGF/EGFR, JAK2, or Src." (PMID 24260381, 2013). "As reported, EGFR and phosphorylated STAT3 were strongly expressed in the nucleus of cancer cells in surgical and biopsy specimens of nasopharyngeal tissues from NPC patients in southern China, suggesting that EGFR- and STAT3-dependent mechanisms are important for carcinogenesis." (PMID 24499623, 2013). "These clinical in situ lesions displayed the same immunophenotype (positive for CK5/6, CK14, CK17 and EGFR, and negative for Her2/neu and ER/PgR) as the invasive basal-like cancer component, suggesting a common precursor lesion." (PMID 23548208, 2013). "In our present study, we also find that high purity NK cells increase autophagy in A549 cancer cells with wide type EGFR, while not in H1975 cells with EGFR L858R + T790M." (PMID 23937717, 2013). "Furthermore, an FUT1- and FUT2-overexpressing cell line proliferates more aggressively than the parent cell line, suggesting that activation of EGFR and HER2 induces a malignant phenotype in human cancer cells." (PMID 23128605, 2013). "Taken together, the elevated ZEB1 expression following EMT may serve as an important mediator that could converge highly activated EGFR-MEK/ERK signaling on MMP2 induction, facilitating the invasion of the EMT-induced cancer cells." (PMID 24318272, 2013). "EMT encompasses many known pathways such as the EGFR, TGF-β, and Wnt-signaling that promote the continuous acquisition of malignant biological features by cancer cells and contributes to the highly invasive nature of certain cancers." (PMID 23054677, 2013). "Because patients with K-RAS mutation do not respond to EGFR inhibitors, understanding the role of RAS in cancer pathophysiology is important, and RAS are being studied as a molecular target therapy for patients who have RAS gene mutation." (PMID 23434665, 2013). "High expression of ERBB3 in certain human cancers led early to the suggestion that it could be a therapeutic target, but in some cancer cells the mesenchymal phenotype was found to lose ERBB3 expression and show resistance to EGFR inhibitors." (PMID 23135478, 2013). "Consequently, EGFR and COX-2 inhibitors have been investigated for chemotherapy and cancer prevention." (PMID 24155892, 2013).